ETS1-AS1 (ETS1 antisense RNA 1)
Synonyms: pancEts-1
Gene: Long non-coding RNA gene on chromosome 11 (128,526,142 to 128,530,389, forward strand). Ensembl gene ENSG00000254588.
Diseases named in the same sentence as ETS1-AS1 in open-access papers:
ETS1-AS1 is named in the same sentence as 1 disease in open-access papers, as found by Europe PMC text mining. Sharing a sentence is not in itself a finding about the gene and the disease.
ETS1-AS1 shares sentences with these, for which no sentence is quoted: neuroblastoma (1 paper).